FTO (FTO alpha-ketoglutarate dependent dioxygenase)
Diseases named in the same sentence as FTO in open-access papers (continued):
Sharing a sentence is not in itself a finding about the gene and the disease.
Nephropathy (6 papers, 2018 to 2025). A nonspecific term referring to disease or damage of the kidneys. "We then detected the mRNA expression of m6A methyltransferases (METTL3, METTL14, and WTAP) and demethyltransferases (FTO and ALKBH5) and found that METTL3 and FTO mRNA expression was upregulated in Pb-induced nephropathy compared with controls." (PMID 40520008, 2025). "An analysis of 40 single-nucleotide polymorphisms (SNPs) in 40 genes of 503 T2DM patients vs. 580 healthy controls on a Sequenom platform identified SNPs in the CAT, FTO and UCP1 genes associated with the retinopathy and nephropathy complications of T2DM." (PMID 36013384, 2022). "The association of the FTO locus with overt nephropathy was not affected by an adjustment for age, sex and BMI (rs9936385, r2 = 1 with rs56094641)." (PMID 30566433, 2018). "In our study, none of the tested FTO SNPs were associated with T2D, but all affected the individual’s risk of nephropathy." (PMID 29410390, 2018).
oral squamous cell carcinoma (6 papers, 2021 to 2025). "Conversely, another study found that silencing FTO in oral squamous cell carcinoma cells increased autophagic flux and suppressed tumorigenesis." (PMID 36263177, 2022). "However, the roles of RNA m6A demethylases, fat mass and obesity-associated protein (FTO), and AlkB homolog 5 (ALKBH5) in oral epithelial dysplasia (OED) and oral squamous cell carcinoma (OSCC) remain unclear." (PMID 36582218, 2023).
psychological distress (6 papers, 2014 to 2022). "A higher rigid control and attitude to self-regulation score may decrease the BMI of the non-risk homozygotes of FTO rs1421085, while an increase in psychological distress (increased GHQ score) may increase their BMI." (PMID 25102252, 2014).
triple-negative breast carcinoma (6 papers, 2021 to 2025). An invasive breast carcinoma which is negative for expression of estrogen receptor (ER), progesterone receptor (PR), and human epidermal growth factor receptor 2 (HER2). "On the other hand, overexpression of the demethylase FTO restrained the proliferation, invasion, and migration in triple-negative breast cancer cells via affecting the miR-17-5p/ZBTB4 axis." (PMID 40002690, 2025). "In Luminal A and triple-negative breast cancer cell lines, FTO suppression fosters apoptosis and impedes cell migration, both in vitro and in vivo." (PMID 39449798, 2024). "Research has shown that inhibition of FTO using MO-I-500, a small molecule inhibitor, effectively suppressed the growth and colony formation of triple negative breast cancer cells." (PMID 35731272, 2023). "Mo-i-500 was recently found to be a selective inhibitor of FTO, which inhibited the proliferation of triple-negative breast cancer cells." (PMID 36389416, 2022). "Six paired samples from two luminal B, two Her2 enriched, and two triple-negative breast cancer (TNBC) patients were used for IHC of METTL3, METTL14, FTO, YTHDF1, and YTHDF3." (PMID 34804948, 2021).
abortion (5 papers, 2022 to 2025). the ending of pregnancy by removing a fetus or embryo before it can survive outside the uterus. "The objective of the study is to examine the association between vitamin E and abortion in individuals with different FTO genotypes." (PMID 41324103, 2025). "The results indicated a significant inverse association between dietary intake of beta-cryptoxanthin and abortion in carriers of the TT genotype of the FTO rs9939609 polymorphism after adjustment for age, BMI, physical activity, smoking, alcohol drinking, and calorie intake." (PMID 39703890, 2024). "The present study was an attempt to explore and analyze the relationship between vitamin E, abortion, and FTO genotypes." (PMID 41324103, 2025). "At the maternal-fetal interface, FTO, IGF2BP1 and IGF2BP2 are decreased in abortion tissues, with a decreased level of FTO-bound HLA-G, VEGFR and MMP9 mRNA." (PMID 37009476, 2023). "At the maternal–fetal interface of women with spontaneous abortion, m6A itself is abnormally accumulated and correlated with the downregulated RNA demethylase FTO." (PMID 35999615, 2022).
alcohol dependence (5 papers, 2014 to 2022). Physical and psychological dependence on alcohol. "Several studies showed that FTO SNPs (including rs8062891, rs1108086, rs1420318, rs12597786 and rs7204609) had significant associations with alcohol dependence." (PMID 36235854, 2022). "Recently, this protective effect of FTO variants on alcoholism has been confirmed by independent studies in other populations." (PMID 25265168, 2014). "If our results were secondary to the described link between FTO variants and alcoholism such an association could be expected as we have previously shown that in Polish population alcoholism and suicide under influence of alcohol frequently co-occur." (PMID 25265168, 2014).
cardiomyopathy (5 papers, 2013 to 2023). A disease of the heart muscle or myocardium proper. "Heart tissues from mice on a high-fat diet (HFD) contained decreased levels (both mRNA and protein) of FTO, which were reversed by intermittent fasting, a nutritional approach improving HFD-induced obesity cardiomyopathy." (PMID 37331009, 2023).
Cognitive impairment (5 papers, 2011 to 2025). Abnormal cognition is characterized by deficits in thinking, reasoning, or remembering. "Collectively, the present study offers compelling evidence that the aberrant m6A demethylase FTO contributes to synaptic and cognitive impairment in neonatal HIBD by activating Akt/mTOR-mediated autophagy through the destabilization of PTEN mRNA." (PMID 38092760, 2023). "Thus, our data show that FTO inhibition ameliorated apparent cognitive impairment of SAMP8-HFD mice." (PMID 39984825, 2025). "Our findings indicate that FTO may play a key role in HI-induced synaptic and cognitive impairment through regulation of autophagy." (PMID 38092760, 2023). "However, there is limited knowledge regarding the possible role of FTO in regulating cognitive impairment induced by HI injury, as well as whether this protective effect may be associated with the inhibition of autophagy activation." (PMID 38092760, 2023). "Our findings demonstrate that the FTO/PTEN axis acts as a critical regulator in HI neonatal rats, linking synaptic and cognitive impairment to autophagy." (PMID 38092760, 2023). "Interestingly, the inhibition of FTO appears to ameliorate cognitive deficits without significantly affecting body weight." (PMID 39984825, 2025).
Infertility (5 papers, 2018 to 2024). "Missense mutations in FTO and ALKBH5 have been identified in men who have undergone infertility testing, showing that m6A is related to abnormalities in male sperm and infertility." (PMID 38937660, 2024). "Our research expands the understanding of the role of m6A modification in regulating the long-term maintenance of spermatogenesis, which is expected to provide new strategies for the treatment of infertile males by using agonists of FTO in the testis." (PMID 37146971, 2023). "Some FTO inhibitors may have potential therapeutic effects on infertility." (PMID 34568313, 2021).
lipid metabolism disorder (5 papers, 2021 to 2026). "Recently, it was identified that triclosan exposure induces lipid-metabolism disorder via downregulation of miR-30b expression to regulate FTO-mediated m6A methylation, which might be a feasible molecular mechanism in HCC." (PMID 33955330, 2021).
preeclampsia (5 papers, 2011 to 2025). Preeclampsia is a hypertensive disorder of pregnancy that is characterized by new-onset hypertension with proteinuria presenting after 20 weeks of gestation, and depending on mild or severe forms may initially present with severe headache, visual disturbances, and hyperreflexia. "This is in contrast to the effect of the FTO variant on preeclampsia, which is disproportionate to its effect on BP." (PMID 33239696, 2020). "We investigated whether the FTO SNP rs9939609 is associated with the risk of preeclampsia (PE) in a Finnish study population." (PMID 22132335, 2011). "We thus conclude that in addition to the variants near ZNF831 and FTO that exhibited genome-wide significance, BP variants at FGF5, SH3B2, and MECOM also associate with preeclampsia." (PMID 33239696, 2020). "In genome-wide association meta-analysis of European and Central Asian mothers, we identify sequence variants that associate with preeclampsia in the maternal genome at ZNF831/20q13 and FTO/16q12." (PMID 33239696, 2020). "The maternal variants at FTO and SH2B3 both associated with gestational hypertension in maternal cases with P = 1.7 × 10−3 and 3.7 × 10−5, respectively, while the other preeclampsia variants did not associate with gestational hypertension." (PMID 33239696, 2020).
renal fibrosis (5 papers, 2016 to 2025). A final common manifestation of a wide variety of chronic kidney diseases characterized by glomerulosclerosis and tubulointerstitial fibrosis. "In animal and cell culture models of renal fibrosis, m6A demethylase FTO has been shown to reduce the m6A decoration of lncRNA GAS5, promoting the EMT process." (PMID 39756462, 2025). "Another m6A eraser, FTO, also contributes to renal fibrosis by regulating different mRNAs." (PMID 39756462, 2025). "It was reported that FTO plays a role in regulating renal fibrosis, and the m6A modification of lncRNA GAS5 may participate in the process." (PMID 36685533, 2022). "Here we show that FTO expression is increased after ureteral obstruction and renal fibrosis." (PMID 26727661, 2016). "Dysregulation of FTO has been reported in various kidney diseases, such as ccRCC, AKI, urethral obstruction, and renal fibrosis." (PMID 36792603, 2023). "Collectively, this study uncovered a previously unrecognized function of canagliflozin in FTO in the autophagy modulation through the regulation of SQSTM1 mRNA stability in the renal tubular STAT6/PPARα/FAO axis and renal fibrosis." (PMID 36685533, 2022).
acute coronary syndrome (4 papers, 2012 to 2025). Signs and symptoms related to acute ischemia of the myocardium secondary to coronary artery disease. "On the other hand, a study conducted on 1092 cases (acute coronary syndrome [ACS]) and 1191 controls declared that the FTO gene variant rs17817449 was significantly associated with ACS in Caucasian males." (PMID 39257882, 2024).
attention deficit-hyperactivity disorder (4 papers, 2014 to 2025). A disorder characterized by a marked pattern of inattention and/or hyperactivity-impulsivity that is inconsistent with developmental level and clearly interferes with functioning in at least two settings (e.g. at home and at school). "Further studies have shown that the FTO SNP rs8050136 is involved in modulating the risk for attention-deficit/hyperactivity disorder (ADHD), especially in children who are not exposed to maternal smoking during pregnancy (MSDP)." (PMID 33162550, 2020).
autoimmune disease (4 papers, 2022 to 2025). A disorder resulting from loss of function or tissue destruction of an organ or multiple organs, arising from humoral or cellular immune responses of the individual to their own tissue constituents. "FTO, which is responsible for the regulation of RNA m6A methylation, is associated with autoimmune disease development." (PMID 39995976, 2025). "For example, since recent studies link FTO with particular auto-immune diseases, it may be worthwhile to investigate whether potential single nucleotide polymorphisms in FTO that may affect its activity could be associated with IFN-related autoimmune diseases." (PMID 39791911, 2025). "The reduced expression of FTO, and ALKBH5 in JIA monocytes mirrors observations in other autoimmune disorders." (PMID 41009809, 2025).
bladder tumors (4 papers, 2021 to 2022). "An increase in protein but not mRNA level was reminiscent of post-translational modification of FTO in bladder tumors." (PMID 33461172, 2021). "Unexpectedly, FTO was negatively correlated with the survival rate of BLCA patients, which is seemingly a paradox in terms of its reduced transcription in bladder tumors." (PMID 33461172, 2021).
bladder urothelial carcinoma (4 papers, 2020 to 2024). "In the present study, we intend to investigate the biological role of fat mass and obesity associated protein (FTO) in human bladder urothelial carcinoma." (PMID 32299393, 2020). "Wen’s study also demonstrated that the expression of FTO mRNA in bladder urothelial carcinoma decreases significantly compared with the normal controls from both the data of real-time PCR (p < 0.05) and TCGA (p < 0.01), which is consistent with our study." (PMID 34521394, 2021). "The aim of the present study is to investigate the biological role of FTO in human bladder urothelial carcinoma." (PMID 32299393, 2020). "First, to fully understand the relationship between FTO and the development of bladder urothelial carcinoma, the effect of overexpression of FTO on 5637 and T24 cells are needed." (PMID 32299393, 2020). "For the limitation of sample size, stageI was excluded for analysis of FTO mRNA expression between bladder urothelial carcinoma and the normal controls." (PMID 32299393, 2020). "We analyzed the expression of FTO mRNA between the bladder urothelial carcinoma tissues and the normal controls from 30 patients following radical cystectomy in the Second Hospital of Dalian Medical University." (PMID 32299393, 2020). "The expression of FTO mRNA in bladder urothelial carcinoma decreases significantly compared with the normal controls from both the data of real-time PCR (p < 0.05) and TCGA (p < 0.01)." (PMID 32299393, 2020). "Although we have conducted a wide range of analyses using data from TCGA to improve our understanding of the relationship between FTO and bladder urothelial carcinoma, some limitations were hard to avoid." (PMID 32299393, 2020). "The expression level of FTO mRNA was significantly down-regulated in stageII-IV of bladder urothelial carcinoma tissues compared with the normal controls (p < 0.0001 for stageII, p = 0.0083 for stageIII and p = 0.0009 for stageIV)." (PMID 32299393, 2020). "In the present study, we surprisingly found that the FTO expression was down-regulated in bladder urothelial carcinoma." (PMID 32299393, 2020). "We analyzed the RNA-Seq data for FTO in different stages (TNM) of bladder urothelial carcinoma samples from TCGA (412 cancerous and 19 normal samples)." (PMID 32299393, 2020). "As far as we know, we are the first one to report the FTO expression and its biological role in bladder urothelial carcinoma." (PMID 32299393, 2020). "The findings in our study indicates that down-regulation of FTO plays an oncogenic role, which may indicate a high m6A level in bladder urothelial carcinoma." (PMID 32299393, 2020). "The presumably RNA demethylase activity of FTO may has important roles in physiological processes in bladder urothelial carcinoma." (PMID 32299393, 2020). "FTO mRNA was significantly down-regulated in bladder urothelial carcinoma tissues (P = 0.0143)." (PMID 32299393, 2020). "Thus, we suppose that FTO may play its role in bladder urothelial carcinoma as an RNA demethylase in the reversible RNA modification." (PMID 32299393, 2020). "PCR and western blotting are used to measure the levels of FTO in both tissues and cell lines (5637, T24, TCCSUP) of human bladder urothelial carcinoma." (PMID 32299393, 2020).
brain tumor (4 papers, 2017 to 2021). "In brain tumors, the two m6A mRNA demethylases FTO and ALKBH5 have been clearly associated to pro-oncogenic functions, promoting cell proliferation, self-renewal, and the progression of GBMSC-initiated tumors." (PMID 33375621, 2020).
cognitive decline (4 papers, 2022 to 2025). "This suggests that inhibiting FTO may have neuroprotective effects in the context of HFD-induced cognitive decline." (PMID 39984825, 2025). "For example, altered METTL3 or YTHDF2 activity in excitatory neurons has been shown to impair long-term potentiation and accelerate cognitive decline, while increased FTO-mediated demethylation in microglia promotes pro-inflammatory cytokine production and blood-brain barrier disruption." (PMID 40624693, 2025). "In conclusion, pharmacological FTO inhibition ameliorated HFD-induced metabolic disturbances and cognitive decline in SAMP8 mice." (PMID 39984825, 2025).
colon adenocarcinoma (4 papers, 2024 to 2025). "Furthermore, histologic subtypes of colonic adenocarcinoma exhibited significantly elevated FTO expression compared to adjacent normal tissues." (PMID 39820532, 2025). "Because TTC7B, FTO, and PI4KA expression is frequently downregulated in many cancers in the TCGA project, including colon adenocarcinoma (COAD), we performed a validation experiment using COAD and paired surgical margin (SM) samples from 105 patients." (PMID 39897037, 2025).
COVID-19 (4 papers, 2022 to 2023). A disease caused by infection with severe acute respiratory syndrome coronavirus 2. "Lastly, we linked RBPs to functional, OMICs and COVID-19 patient data from other studies, and identified MBNL1, FTO and FXR2 RBPs as potential clinical biomarkers." (PMID 36814457, 2023). "COVID-19 patients with high expression levels of FTO tend to display high levels of METTL3, METTL16, RBM15B, or VIRMA." (PMID 35655464, 2022). "Significant positive correlations were observed between METTL3, METTL16, RBM15B, VIRMA, and FTO in COVID-19 patients." (PMID 35655464, 2022). "Some of DEGs may be associated with the varying severity of COVID-19, such as METTL3, FTO, and RBM15." (PMID 35655464, 2022).
eating disorder (4 papers, 2017 to 2024). A broad group of psychological disorders with abnormal eating behaviors leading to physiological effects from overeating or insufficient food intake. "Also, FTO A allele has also been associated with increased severity of eating disorders like binge eating behavior or psychopathological features, including emotional eating and disorder of corporeality." (PMID 39130748, 2024).
endotoxemia (4 papers, 2022 to 2023). "Endotoxemia inhibited myocardial expression of fat mass- and obesity-associated protein (FTO), an m6A eraser/demethylase." (PMID 34581943, 2022). "Moreover, elevated m6A-RNA methylation and FTO repression were causatively involved in myocardial inflammation and dysfunction during endotoxemia in mice." (PMID 35402566, 2022). "In conclusion, our data demonstrates that endotoxemia alters the expression of m6A demethylase FTO and subsequent m6A methylation in the cardiac tissue." (PMID 34581943, 2022). "In the present study, we investigated the influence of LPS-induced endotoxemia on cardiac m6A-RNA modification and FTO expression." (PMID 34581943, 2022). "We demonstrated that LPS-induced endotoxemia increases global m6A-RNA methylation in the mouse myocardium with a significant downregulation of FTO and LV functions." (PMID 34581943, 2022). "In endotoxemia, downregulation of erasers (e.g., FTO) leads to enhanced m6A methylation of inflammatory cytokines in the myocardium." (PMID 34581943, 2022). "For example, in lipopolysaccharide (LPS)-induced endotoxemia on myocardial inflammation, the m6A-RNA methylation level and inflammatory cytokine genes increased, while FTO knockdown mimicked the effects." (PMID 35840562, 2022). "Similarly, the expression of FTO is decreased in the myocardium of mice with lipopolysaccharide (LPS)-induced endotoxemia, and FTO knockdown in cardiomyocytes mimics the LPS-induced effect." (PMID 36781867, 2023). "However, despite its functional importance in various fundamental biological processes, the role of FTO-dependent m6A RNA modification in the myocardium during endotoxemia and its implications is still unknown." (PMID 34581943, 2022).